IL10RA (interleukin 10 receptor subunit alpha)
Description:
Cell surface receptor for the cytokine IL10 that participates in IL10-mediated anti-inflammatory functions, limiting excessive tissue disruption caused by inflammation. Upon binding to IL10, induces a conformational change in IL10RB, allowing IL10RB to bind IL10 as well. In turn, the heterotetrameric assembly complex, composed of two subunits of IL10RA and IL10RB, activates the kinases JAK1 and TYK2 that are constitutively associated with IL10RA and IL10RB respectively. These kinases then phosphorylate specific tyrosine residues in the intracellular domain in IL10RA leading to the recruitment and subsequent phosphorylation of STAT3. Once phosphorylated, STAT3 homodimerizes, translocates to the nucleus and activates the expression of anti-inflammatory genes. In addition, IL10RA-mediated activation of STAT3 inhibits starvation-induced autophagy.
Synonyms: IL-10R1; CD210; IL10R; HIL-10R; CDW210A; CD210a
Tractability: Antibody: UniProt places it where antibodies can reach, with high confidence; its Gene Ontology location is reachable by antibodies, with high confidence; UniProt predicts a signal peptide or a membrane-spanning region; the Human Protein Atlas places it where antibodies can reach. PROTAC: UniProt records ubiquitination sites on it. Other modalities: a drug acting on it is in phase 2 or 3 trials.
Gene: Protein-coding gene on chromosome 11 (117,986,370 to 118,003,037, forward strand). Ensembl gene ENSG00000110324.
Subcellular location: Cell membrane; Cytoplasm
Subcellular location (Human Protein Atlas): Cytosol; Plasma membrane; Primary cilium
Pathways (Reactome):
Disease: Nuclear events stimulated by ALK signaling in cancer
Immune System: Interleukin-10 signaling
Gene Ontology:
Molecular function: interleukin-10 receptor activity; protein binding; signaling receptor activity; interleukin-10 binding
Biological process: interleukin-10-mediated signaling pathway; intestinal epithelial structure maintenance; negative regulation of autophagy; negative regulation of inflammatory response; positive regulation of receptor signaling pathway via JAK-STAT; ubiquitin-dependent endocytosis; cell surface receptor signaling pathway via JAK-STAT; cytokine-mediated signaling pathway; positive regulation of cell population proliferation; positive regulation of tyrosine phosphorylation of STAT protein; regulation of synapse organization; response to lipopolysaccharide
Cellular component: apical plasma membrane; cytoplasm; cytosol; interleukin-10 receptor complex; plasma membrane
Genetic constraint (gnomAD): Loss-of-function variants: 19 observed, 31.03 expected, observed/expected ratio (o/e) 0.61, 90% interval 0.43 to 0.9. The upper end of that interval is the gene's LOEUF score, 0.9, which puts it in group 3 of 6, group 1 being the genes least tolerant of losing a copy. Missense variants: 634 observed, 740.1 expected, observed/expected ratio (o/e) 0.86, 90% interval 0.8 to 0.92. Synonymous variants: 292 observed, 302.15 expected, observed/expected ratio (o/e) 0.97, 90% interval 0.88 to 1.07.
Gene-disease validity (ClinGen):
ClinGen rates the evidence that IL10RA causes each of these diseases.
inflammatory bowel disease 28 (autosomal recessive): Definitive.
Homologues: Orthologues: chimpanzee IL10RA (99% identical), macaque IL10RA (93% identical), dog IL10RA (72% identical), pig IL10RA (71% identical), guinea pig IL10RA (64% identical), rabbit IL10RA (63% identical), mouse Il10ra (56% identical), rat Il10ra (56% identical), tropical clawed frog il10ra (22% identical), zebrafish crfb15 (8% identical), zebrafish ifnlr1 (8% identical), zebrafish ifngr2 (8% identical), and 4 more. Paralogues in human: IL22RA1 (19% identical), IL20RA (14% identical), IFNLR1 (12% identical), IFNAR2 (11% identical), IFNGR1 (10% identical), IL10RB (10% identical), IL22RA2 (10% identical), IFNAR1 (10% identical), IFNGR2 (9% identical), IL20RB (8% identical), F3 (8% identical).
Diseases named in the same sentence as IL10RA in open-access papers:
IL10RA is named in the same sentence as 196 diseases in open-access papers, as found by Europe PMC text mining. Sharing a sentence is not in itself a finding about the gene and the disease. The quoted sentences say what the papers report.
colitis (84 papers, 2010 to 2025). Inflammation of the colon. "Mutations in IL10 or the genes encoding its receptors IL10RA/IL10RB in humans were shown to cause autosomal recessive disease with CD-like colitis and GWAS studies have identified associations between these three genes and sporadic IBD." (PMID 30410494, 2018). "Macrophage-specific conditional deletion of at least two IBD susceptibility loci, Il10ra and Stat3 knockout has been shown to generate spontaneous colitis in mice." (PMID 28263993, 2017). "From early infancy, the patient manifested refractory colitis, perianal disease and folliculitis, in addition to associated hematologic disorders, which may also be the result of the IL10RA genetic defect." (PMID 26822028, 2016). "As far as CD is concerned, the relevance of the IL-10 pathway in dampening inflammation was substantiated by the development of severe colitis in infants with mutations of IL-10, IL-10RA, or IL-10RB genes and in mice deficient in IL-10 that underwent spontaneous development of colitis." (PMID 26206376, 2015). "In humans, mutations to the IL10RA and IL10RB genes have both been strongly associated with infant colitis associated with defects in downregulation of proinflammatory cytokine secretion by monocytes." (PMID 37600781, 2023). "Although we demonstrated reduced accumulation of immature macrophages and reduced severity of colitis in Cdcs1+/+Il10ra−/−Ccr2−/− mice compared to Cdcs1+/+Il10ra−/− mice, Cdcs1+/+Il10ra−/−Ccr2−/− mice continued to develop colitis of moderate severity." (PMID 35013585, 2022). "While MNP-Runx3Δ and MNP-Il10RΔ mice displayed a similar spontaneous colitis phenotype with a significant overlap of RM up-regulated genes, expression of Il10ra and Il10rb was unaffected in Runx3Δ RM." (PMID 32453801, 2020). "A significant up-regulation of genes encoding the following cytokines and their receptors—Il13, Il16, Il27, Il2rb, Il2rg, Il6r Il10ra, Faslg, Ltb, Osm, Spp1, Tnf, Tnfsf14—was noted in animals with colitis (CβG−)." (PMID 31590413, 2019). "In another inflammation model, experimental colitis, blocking miR-142-5p expression ameliorates disease by IL-10RA pathway." (PMID 30687316, 2018). "Blocking miR-142-5p reduced colitis and prevented wasting disease, possibly by activation of the IL10RA pathway." (PMID 29059189, 2017). "Polymorphisms in genes encoding for subunits of the IL-10 receptor (IL10RA, IL10RB) are also associated with human IBD, particularly very early onset colitis." (PMID 29118930, 2017). "Three homozygous mutations in IL10RA and IL10RB were identified from 4 of 9 patients with early onset colitis." (PMID 29118930, 2017). "Three homozygous mutations in IL10RA and IL10RB were identified in four out of nine patients with early onset colitis." (PMID 29118930, 2017). "While the CD4+CD45RO+hi transfer colitis model showed a gene expression profile concordant with inhibition of IL10RA, treatment with anti-miR-142-5p was concordant with induction of IL10RA and reduction in colitis." (PMID 29059189, 2017). "A key suppressor of macrophage-associated inflammation is the IL-10/IL-10 receptor (IL-10R) axis, as mice bearing mutations in IL10-Ra in intestinal CX3CR1+ macrophages developed severe colitis comparable to the pathology reported for IL-10-deficient animals." (PMID 26082775, 2015). "The investigators identified three distinct homozygous mutations in genes IL10RA and IL10RB, encoding the IL10R1 and IL10R2 proteins in four out of nine patients with early-onset colitis." (PMID 24454343, 2013). "The crucial role of IL-10 within the colonic mucosa is evidenced by infants carrying mutations in IL10 (interleukin 10), IL10RA (interleukin 10 receptor subunit alpha) or IL10RB (interleukin 10 receptor subunit beta), who develop severe colitis within the first weeks of life." (PMID 41010030, 2025).
colitis (continued). "Indeed similar to our study it has recently been shown that specific deletion of the Il10ra in CX3CR1+ cells elicits spontaneous colitis in a Helicobacter positive facility." (PMID 27027442, 2016). "We have shown that the absence of IL10RA leads to the rapid development of infant-onset colitis in C57BL/6 mice that also harbor Cdcs117." (PMID 35013585, 2022). "However, we found that the histological signs of colitis were less severe in Cdcs1+/+ mice that lacked both Il10ra and Ccr2 than in littermates that lacked Il10ra alone." (PMID 35013585, 2022).
inflammatory bowel disease (47 papers, 2012 to 2026). A spectrum of small and large bowel inflammatory diseases of unknown etiology. "In East Asia, IL10RA is the predominant pathogenic gene in patients with very early-onset inflammatory bowel disease (VEO-IBD), frequently characterised by refractory diarrhoea and severe perianal disease, resulting in elevated death rates." (PMID 40611267, 2025). "The silent variant of IL10RA has been reported in patients with IL10RA-related inflammatory bowel disease." (PMID 37325673, 2023). "We systematically investigated the prevalence, structural, and functional consequences of pathogenic IL10RA variants that are associated with monogenic inflammatory bowel disease." (PMID 36370291, 2023). "We describe a novel exonic mutation in the IL10RA gene resulting in infantile-onset inflammatory bowel disease." (PMID 26822028, 2016). "Therefore, this study performed the multidimensional computational analysis of IL10RA missense variations causative to pediatric or early onset inflammatory bowel disease (<5 years of age)." (PMID 29755507, 2018). "Here we report a novel exonic mutation in the IL10RA gene that caused unique splicing aberrations in a Japanese patient with infantile-onset of inflammatory bowel disease in association with immune thrombocytopenic purpura and a transient clinical syndrome mimicking juvenile myelomonocytic leukemia." (PMID 26822028, 2016). "The importance of IL-10 in intestinal immunity is also illustrated by the identification of mutations in IL-10, IL-10RA, and IL-10RB genes in children suffering from inflammatory bowel disease (IBD)." (PMID 30915067, 2019). "Similarly, mutations in the IL10RA gene, particularly prominent in early-onset inflammatory bowel disease (IBD), disrupt critical anti-inflammatory pathways, allowing unrestrained inflammatory responses that damage the intestinal villi." (PMID 40724600, 2025). "Very early-onset inflammatory bowel disease (VEOIBD), caused by defects in interleukin-10 (IL-10) signaling, including defects in IL10, IL10RA, and IL10RB, is an autosomal recessive disorder." (PMID 37986047, 2023). "It has been shown that individuals with severe immune-mediated diseases, such as very early onset inflammatory bowel disease (VEOIBD) and autoimmune thyroid diseases, have polymorphisms in IL-10 and its receptors, IL-10RA and IL-10RB." (PMID 36992353, 2023). "Loss of function mutations affecting any of the two genes encoding interleukin-10 receptor (IL10RA or IL10RB genes); or affecting the gene encoding the cytokine IL-10 (IL-10 gene), will cause early-onset inflammatory bowel disease." (PMID 32737687, 2020). "Accordingly, defects of IL10, IL10RA, or IL10RB genes cause very early-onset inflammatory bowel disease (IBD) including infantile-onset IBD (IOIBD)." (PMID 26822028, 2016). "There are, however, certain rare forms of IBD, particularly in pediatric patients, that can be classified as monogenic, which are caused by mutations in single genes like IL10RA, IL10RB, or XIAP genes, and often present as very early-onset inflammatory bowel disease (VEO-IBD)." (PMID 40611267, 2025).
melanoma (12 papers, 2009 to 2026). A malignant, usually aggressive tumor composed of atypical, neoplastic melanocytes. "Previous studies showed IL10RA was highly related to the clinical outcomes of colorectal cancer and melanoma." (PMID 33859933, 2021). "Further in vitro biochemical experiments, including CCK8 assays, wound-healing assays and transwell assays, have verified that IL10RA can significantly inhibit the proliferation, migration and invasion of melanoma cells." (PMID 33490091, 2020). "We further conducted in-vitro experiments to validate the function of IL10RA in inhibiting the proliferation, migration and invasion of melanoma cells." (PMID 33490091, 2020). "We have conducted further in-vitro biochemical experiments, including CCK8 assays, wound-healing assays and transwell assays, and verified that IL10RA can significantly inhibit the proliferation, migration and invasion of melanoma cells." (PMID 33490091, 2020). "Therefore, wound healing assays demonstrated that knockdown of IL10RA can promote the migration of melanoma cells compared to control groups." (PMID 33490091, 2020). "We next tested whether IL10RA can affect the migration of melanoma cells." (PMID 33490091, 2020). "Therefore, we speculate that IL10RA may inhibit the metastasis of melanoma by regulating the PI3K-AKT signaling pathway, which we plan to do further exploration to verify the mediation of IL10RA in PI3K-AKT pathway." (PMID 33490091, 2020).
enterocolitis (8 papers, 2016 to 2024). An inflammatory process affecting the small intestine and colon. "Children with mutations in Il-10, Il-10RA and Il-10RB genes manifested with severe enterocolitis with perianal lesions and penetrating behavior within first months of life." (PMID 38137450, 2023). "Also patients with deleterious mutations in IL10, IL10RA or IL10RB develop severe enterocolitis in the first few months of life." (PMID 33240582, 2020).
Autoimmunity (7 papers, 2015 to 2025). The occurrence of an immune reaction against the organism's own cells or tissues. "The other nodes of the network mainly contain genes/proteins related to autoinflammatory/autoimmunity, such as JAK1, STAT3, STAT5B, IL10RA, and IL10RB, with SOCS3 as a hub." (PMID 39359477, 2024).
colorectal cancer (7 papers, 2019 to 2022). A primary or metastatic malignant neoplasm that affects the colon or rectum. "The expression of IL10RA is also considered to be associated with the clinical stage of colorectal cancer." (PMID 35432443, 2022). "IL10RA encodes a receptor molecule for the inflammatory factor IL10 and is associated with IL10 expression and STAT3 phosphorylation in colorectal cancer." (PMID 35432443, 2022). "They reported IL10RA as one of hub genes with a lower mRNA expression in colorectal cancer samples compared to normal." (PMID 35486660, 2022). "Interleukin 10 receptor subunit alpha (IL10RA) regulates tumor immune responses and is implicated in the pathogenesis of colorectal cancer." (PMID 35480305, 2022). "In colorectal cancer, the expression of IL10RA is found to be higher in healthy tissue than in the CRC tissue and showed association with the proliferation index, confirming the importance of IL10RA in the pathogenesis of CRC." (PMID 33604283, 2020). "IL10RA showed higher expression in healthy colon samples compared to colorectal cancer." (PMID 35486660, 2022).
COVID-19 (7 papers, 2021 to 2025). A disease caused by infection with severe acute respiratory syndrome coronavirus 2. "After adjustment for confounding factors, seven proteins that were highly abundant and associated with an increased hazard of critical COVID-19 outcome were SLAMF1, CCL25, IL2RB, IL10RA, IL15RA, IL18 and CST5." (PMID 40475767, 2025). "The respective APNet bipartite graph contained a large cluster (IL10RA, ACTN4, ITGB2, IL2RB, BIRC2, ITGAM, HMOX1, TIMP1) linked with established COVID-19 inflammatory and immune signalling cascades." (PMID 39921901, 2025). "Here, we demonstrated that the unique signature featuring SLAMF1, CCL25, IL2-RB, IL10RA, IL15RA, IL18, and CST significantly increased the risk of critical illness in COVID-19 patients." (PMID 40475767, 2025). "Levels of SLAMF1, CCL25, IL2RB, IL10RA, IL15RA, IL18 and CST5 were significantly upregulated in patients with critical COVID-19 illness compared to individuals negative for COVID-19." (PMID 40475767, 2025).
Arthritis (6 papers, 2016 to 2021). Inflammation of a joint. "In our model, suppression of arthritis following α-GalCer was IL-10 independent as there was equivalent suppression of the disease in α-GalCer-treated Il10ra−/− and WT mice." (PMID 29449556, 2018).
lymphoma (6 papers, 2011 to 2025). A malignant (clonal) proliferation of B- lymphocytes or T- lymphocytes which involves the lymph nodes, bone marrow and/or extranodal sites. "Moreover, it has been reported that the IL10RA Ser138Gly variant showed a weak association with the risk of all lymphoma combined (odds ratio [OR], 0.81; 95% CI, 0.65–1.02), mainly driven by the 50% risk reduction for Hodgkin's lymphoma (HL)." (PMID 33490091, 2020).
abscesses (5 papers, 2016 to 2021). "While infant Cdcs1+/+Il10ra+/- mice (control) were asymptomatic, 100% of Cdcs1+/+Il10ra-/- mice developed moderate multifocal proliferative granulocytic colitis with crypt abscesses and loss of goblet cells at 3 weeks." (PMID 28678006, 2017).
Crohn disease (5 papers, 2020 to 2024). A gastrointestinal disorder characterized by chronic inflammation involving all layers of the intestinal wall, noncaseating granulomas affecting the intestinal wall and regional lymph nodes, and transmural fibrosis. "Both patients with IL-10RA deficiency and those with Crohn’s disease showed a decrease in diversity of gut microbiome." (PMID 33572538, 2021). "Microbiota composition was investigated in 17 patients with IL10RA mutations, 17 patients with pediatric Crohn’s disease, and 26 healthy children." (PMID 33572538, 2021). "This study aimed at exploring whether any fecal microbiota could be associated with engraftment failure following UCBT in Crohn’s disease patients with IL10RA deficiency." (PMID 33162889, 2020).
Immunodeficiency (5 papers, 2020 to 2025). Failure of the immune system to protect the body adequately from infection, due to the absence or insufficiency of some component process or substance. "Therefore, for IL10RA-mutated VEOIBD, opportunistic infection should be considered because of immunodeficiency disorders." (PMID 33849446, 2021).
leukemia (5 papers, 2021 to 2025). A malignant (clonal) hematologic disorder, involving hematopoietic stem cells and characterized by the presence of primitive or atypical myeloid or lymphoid cells in the bone marrow and the blood. "Our previous study revealed that IL-10RA is overexpressed in most AML cells and played an essential role in promoting the stemness of leukemia cells." (PMID 34392305, 2021).
malaria (5 papers, 2013 to 2023). Malaria is a serious and sometimes fatal disease caused by a parasite that commonly infects a certain type of mosquito which feeds on humans. "Reasons may be less biological benefit of the heterozygous IL10RA variants compared to the Sickle cell disease causing hemoglobin variants that confer selective advantage in the malaria setting and higher mortality of IL10RA variants in the homozygous state." (PMID 36370291, 2023). "In addition, a new promoter IL10RA variant (ss491228441) contributes to shield against mild malaria." (PMID 23297791, 2013). "Recently combined promoter haplotypes of the IL10RA and IL10RB genes have been shown to be associated with protection against severe malaria in Gabonese children." (PMID 23297791, 2013). "To summarize, selected regulatory SNPs in the promoter region of FOXP3, IL10RA, IL10RB, STAT6 and TNFRSF18 genes have been investigated for possible association with uncomplicated malaria and high P. falciparum parasite density among Congolese children." (PMID 23297791, 2013). "In addition, a new SNP detected in the promoter region of IL10RA (ss491228441) contributes to protection against clinical malaria." (PMID 23297791, 2013).